RN7SL353P (RNA, 7SL, cytoplasmic 353, pseudogene)
Synonyms: RN7SL579P
Gene: Miscellaneous RNA gene on chromosome 6 (30,751,038 to 30,751,289, forward strand). Ensembl gene ENSG00000263608.
Homologues: Paralogues in human: RN7SL525P (87% identical), Metazoa_SRP (86% identical), RN7SL602P (85% identical), Metazoa_SRP (85% identical), Metazoa_SRP (84% identical), RN7SL387P (84% identical), RN7SL718P (84% identical), Metazoa_SRP (83% identical), Metazoa_SRP (82% identical), RN7SL121P (81% identical), Metazoa_SRP (81% identical), RN7SL524P (80% identical), and 712 more.